KLK5 (kallikrein related peptidase 5)
Diseases named in the same sentence as KLK5 in open-access papers (continued):
Sharing a sentence is not in itself a finding about the gene and the disease.
breast carcinoma (continued). "KLK5, for instance, was reported to be downregulated in breast cancer, whereas elevated expression of KLK6, KLK7 and KLK10 has been associated with multiple cancers and poor prognosis in gastric and colorectal cancer." (PMID 29263803, 2016). "Validation from The Cancer Genome Atlas (TCGA) database indicated KLK5 was specifically down-regulated in luminal B and basal-like breast cancer subtypes." (PMID 25593998, 2014). "In order to assess potential clinical implications of the KLK5-miR-183-5p axis in breast cancer behavior, we examined the expression of these molecules in breast cancer tissues from patients through the TCGA databases." (PMID 25593998, 2014). "For the first time, we present evidence that KLK5 inhibits breast cancer in vitro and in vivo, consistent with the emerging concept that certain proteases act as tumor suppressors." (PMID 24158494, 2014). "We recently showed that KLK5 exerts tumour suppressive effects by inhibiting the mevalonate pathway in breast cancer cells, thus, inhibiting the activation of signaling oncoproteins due to inhibited prenylation." (PMID 25593998, 2014). "KLK5 has been reported to be dysregulated in breast cancer with its over-expression is indicative of good prognosis." (PMID 25593998, 2014). "KLK5 affected the expression of a network of miRNAs, which are known to inhibit invasion and metastasis in breast cancer." (PMID 25593998, 2014). "Consistent with inhibited biosynthesis of isoprenoids we detected markedly reduced levels of active (i.e. geranylgeranylated) RhoA in KLK5-expressing breast cancer cells." (PMID 24158494, 2014). "Reduced expression of KLK5 has been observed in breast cancers, and in malignant compared to benign breast tissue." (PMID 25593998, 2014). "We aimed to study the putative effects of restored KLK5 expression on the phenotype of the highly aggressive MDA-MB-231 breast cancer cell line in which the expression of KLK5 is completely inactivated." (PMID 24158494, 2014). "Analysis of TCGA data validated the link between the identified KLK5-miRNA axis and breast cancer subtypes." (PMID 25593998, 2014). "Expression of miRNA-183 positively correlated to KLK5 expression, with the highest miR-183 levels in basal-like breast cancers." (PMID 25593998, 2014). "Using over 500-patient samples comprised of 80 basal-like, 128 luminal B, 231 luminal A, and 57 Her2 overexpressing breast cancers, we found that KLK5 expression was significantly reduced in the luminal B subtype as compared with basal-like breast cancers." (PMID 25593998, 2014). "We show for the first time that KLK5 can affect breast cancer pathogenesis through miRNA-mediated pathways." (PMID 25593998, 2014). "Present study aims to investigate the functional KLK5 mediated miRNA network on breast cancer progression, molecular subtype and survival." (PMID 25593998, 2014). "It suggests biological differences between breast cancer molecular subtypes, patient survival, and their propensity for invasion and metastasis can be explained in part by altered miRNA networks induced by KLK5 dysregulation." (PMID 25593998, 2014). "The down-regulation of the KLK5 expression in breast neoplasia does not confirm previous studies, which showed elevated concentration levels of the KLK5 protein in the serum of breast cancer patients, compared to those bearing benign tumors." (PMID 21906360, 2011). "The differential diagnostic impact of the KLK5 expression levels between the malignant and the benign breast tumors as well as the use of the KLK5 expression analysis for the prediction of breast cancer was also assessed by ROC analysis." (PMID 21906360, 2011). "The reduced KLK5 transcription in the malignant cells was also revealed by the breast cancer patients' KLK5 expression analysis in quartiles, compared to the same analysis of the control cohort of patients with benign breast modifications." (PMID 21906360, 2011).
breast carcinoma (continued). "Apart from breast cancer, the prognostic value of KLK5 expression has already been demonstrated for ovarian, bladder, prostate, colorectal and testicular cancer." (PMID 21906360, 2011). "Significantly decreased KLK5 transcription was detected in tissues of breast cancer patients compared to those bearing benign tumors." (PMID 21906360, 2011). "On the other hand, coordinated up-regulation of KLK5, 6, 7, 8, 10, 11 and 14 in ovarian cancer and down-regulation of KLK5, 6, 8, and 10 in breast cancer has been observed." (PMID 21072173, 2010). "We provide evidence that at least four kallikreins are downregulated in breast cancer, and experimentally verified the downregulation of of these kallikreins (KLK5 and KLK12) by RT – PCR." (PMID 14710225, 2004). "A noteworthy observation is the presence of a group of closely localised kallikreins (KLK5, 6, 8, 10, 11 and 14) with a similar pattern of differential expression in breast cancer." (PMID 14710225, 2004). "X-profiler comparison of two pools of normal and breast cancer libraries further verified the presence of significant downregulation of expression levels of 4 of the kallikreins genes (KLK5, 6, 10, 12)." (PMID 14710225, 2004). "We have also previously shown that KLK5 mRNA is highly expressed in normal breast tissue and found potential prognostic significance of KLK5 expression in breast cancer." (PMID 14710225, 2004). "Our results indicate that at least four kallikrein genes (KLK5, 6, 8, 10) are downregulated in breast cancer." (PMID 14710225, 2004). "However, KLK5 has been reported as a suppressor of breast cancers, inhibiting the mevalonate pathway and inducing miRNA-mediated antioncogenic pathways." (PMID 37176127, 2023). "Moreover, reactivation of KLK5 not only suppresses key EMT genes in breast cancer but also suppresses the mevalonate pathway." (PMID 38090381, 2023). "Downregulation of KLK5 expression levels was observed in breast cancer specimens compared with benign specimens and exhibited a significant and independent value for the discrimination of malignant from benign mammary gland biopsies in logistic regression and receiver‐operating curve analysis." (PMID 38090381, 2023). "We found that KLK5 was markedly expressed in breast cancers using GEPIA." (PMID 38090381, 2023). "Among the 20 top clusters of enriched sets, extracellular matrix organization (GO:0030198) and cell‐cell adhesion via plasma‐membrane adhesion molecules (GO:0098742) were directly correlated with EMT, which indicated KLK5 was possibly involved in EMT in breast cancer." (PMID 38090381, 2023). "We next analyzed the expression of KLK5 in breast cancer using different databases." (PMID 38090381, 2023). "We also provide evidence that the KLK5-miRNA-ECM axis could be related to the biological differences between the breast cancer subtypes." (PMID 25593998, 2014). "Recently, we showed KLK5 reconstitution in breast cancer cell lines suppresses malignancy." (PMID 25593998, 2014). "Reportedly, KLK5 displays reduced or inactivated expression in breast cancers but the potential functional consequences in tumor development and/or progression are still unknown/yet to be described." (PMID 24158494, 2014). "Here, we show that KLK5 may act to suppress breast cancer by inhibiting EMTs and, surprisingly, by repressing the mevalonate pathway of cholesterol metabolism." (PMID 24158494, 2014). "We aimed to investigate whether re-expression of the KLK5 protease - reportedly inactivated in the vast majority of mammary carcinomas - may pose functional consequences for tumor growth and/or dissemination." (PMID 24158494, 2014). "Therefore, we investigated KLK5-miRNA networks of interaction and their potential effects on the pathogenesis of breast cancer." (PMID 25593998, 2014). "In conclusion, we show that KLK5 attenuates tumorigenicity of invasive breast cancer cells in vitro and in vivo and may represent a putative Class II tumor suppressor." (PMID 24158494, 2014).
breast carcinoma (continued). "Oncomine analysis of data derived from microarray-based gene expression profiling studies employing established patient datasets showed that KLK5 expression is significantly down-regulated or completely inactivated in the majority of breast cancers of different subtypes compared to normal tissues." (PMID 24158494, 2014). "In particular, sensitivity of IgYs for detection of endogenous KLK6 and lack of crossreactivity with other KLKs and unrelated proteins was assessed by analyzing whole cell lysates and supernatants isolated from MDA-MB-468 breast cancer cell line that expresses the KLK5, KLK6 and KLK10 proteins." (PMID 23216878, 2012). "Indeed, the fact that KLK5 expression was shown to constitute a tumor size-independent biomarker for breast cancer prediction highlights its significance for the discrimination of malignant lesions at an early stage of the disease." (PMID 21906360, 2011). "The study of the association between the KLK5 expression and the ER status revealed a strong negative correlation in the breast cancer patients' cohort." (PMID 21906360, 2011). "In more details, post-menopausal breast cancer women displayed a significant downregulated KLK5 expression profile, with 70.2% of them to be classified as KLK5-negative, compared to the pre-/peri-menopausal ones, of whom only the 40.2% of them were categorized as KLK5-negative." (PMID 21906360, 2011). "Moreover, the down-regulation of the KLK5 expression was also confirmed in breast cancer metastases compared to primary cancer cores, thus highlighting the downregulation of the KLK5 expression throughout breast cancer progression." (PMID 21906360, 2011). "Therefore, KLK5 expression quantification is critical for both the discovery of the early cellular and molecular alterations in breast cancer cells, as well as for the identification of novel diagnostic and prognostic biomarkers." (PMID 21906360, 2011). "Moreover, KLK5 expression levels correlate with the pre-menopausal status (p < 0.005) as well as the ER-negative staining (p = 0.028) of women with breast cancer." (PMID 21906360, 2011). "The univariate logistic regression analysis clearly shows the statistically significant (p < 0.001) negative correlation between the KLK5 expression levels and the risk of a patient to suffer for breast cancer." (PMID 21906360, 2011). "Followingly, they indicated that expression of KLK5, 6, 8, and 12 genes was downregulated in the breast carcinoma tissues compared to normal breast tissues, which suggests imbalanced expression of KLK members is associated with the development of breast cancers." (PMID 37176127, 2023). "Furthermore, in breast cancer cells, KLK5 overexpression was shown to result in down-regulation of a multitude of miRNAs and up-regulation of another set of mRNAs, finally affecting miRNA networks involved in post-transcriptional gene regulation of ECM molecules and cell adhesion pathways." (PMID 31307411, 2019). "Interestingly, expression of KLK5 was high in basal-like and normal-like breast cancer subtypes with a reduction in levels in luminal B. There was reduced expression in normal tissue and basal subtypes with higher expression in luminal (ER+) and Her-2 subtypes for ITGB5, EZR, COL12A1, and COL24A1." (PMID 25593998, 2014). "Also, miR-206 and miR-19a were also demonstrated to have a positive correlation with KLK5 levels with elevated expression in basal-like breast cancers, whereas miR-10b expression was inversely correlated to KLK5 expression with the lowest levels in patients with basal-like breast cancers." (PMID 25593998, 2014). "Our PCA analysis suggests that SOD2, KLK5, KLK7, and IL8 play a significant role in the worsening of breast cancer pathology." (PMID 40426890, 2025). "Breast cancer patients with basal‐like and TNBC subtypes expressed higher KLK5 levels, which was consistent with our bioinformatic analysis results." (PMID 38090381, 2023).
breast carcinoma (continued). "The mRNA levels of both KLK5 and KLK7 were downregulated in breast cancers relative to normal and benign tissues, and downregulated in metastases compared to primary cancers." (PMID 38137332, 2023). "According to a study, the value of the kallikrein-related peptidase 5 gene KLK5 and KLK7 in the diagnosis and prognosis prediction of breast cancer patients was far from clear." (PMID 38137332, 2023). "Higher expression of KLK5 correlated with higher levels of miR-183-5p, lower ITGB1 expression, and a basal-like breast cancer subtype." (PMID 25593998, 2014). "We demonstrated that KLK5, and a combined KLK5 scoring that includes ECM genes can predict breast cancer patient survival as well the differentiating between breast cancer subtypes." (PMID 25593998, 2014). "Lower expression of KLK5 and miR-183-5p was correlated with higher ITGB1 expression and a luminal A or B breast cancer subtype in these patients." (PMID 25593998, 2014). "KLK5 is considered the physiological activator of KLK7 and both serve as serological biomarkers, indicators of poor prognosis, and have a role in tumor invasion and angiogenesis in breast cancer." (PMID 40426890, 2025). "In our study, KLK5 showed low expression in breast cancer but had no significant clinical value in breast cancer without precise molecular subtypes." (PMID 38090381, 2023). "On the other hand, KLK-mediated degradation of extracellular matrix proteins facilitates tumor cell invasion and metastasis, and higher serum levels of other kallikreins such as KLK5, KLK10, and KLK14 have been found in women with breast cancer when compared to healthy ones." (PMID 32344524, 2020). "Furthermore, KLK5 and KLK7 are co-expressed in different cancer types such as breast cancer or oral squamous cell carcinoma." (PMID 33087135, 2020). "KLK5 not only regulates KRT19 expression to increase the malignancy of ovarian cancer cells strongly, but also induces miRNA-mediated anti-oncogenic pathways in breast cancer." (PMID 31572680, 2019). "Here, we show that reconstitution of KLK5 expression in non-expressing MDA-MB-231 breast cancer cells suppresses malignancy in vitro and in vivo dose-dependently." (PMID 24158494, 2014). "The relative quantification of the KLK5 mRNA expression was performed with the use of the comparative CT (2-ΔΔCT) method, whereas the HPRT1 was employed as endogenous reference gene and the BT20 breast cancer cell line as the calibrator of the assay." (PMID 21906360, 2011). "The KLK5 expression of the benign tissue specimens ranged between 0.035-1380.4×103 KLK5 mRNA copies/103 HPRT1 mRNA copies (c/Kc), while the expression in the tissue specimens obtained by the breast cancer patients varied between 0.035-19.6x103 c/Kc." (PMID 21906360, 2011). "A statistically significant (p < 0.001) ability of the KLK5 expression analysis to distinguish breast cancer patients from those bearing non-cancerous breast alterations, was illustrated by the increased AUC (AUC = 0.829; 95%CI = 0.743-0.916)." (PMID 21906360, 2011). "With respect to breast cancer in particular, several kallikrein family members, namely KLK3, KLK5, KLK6, KLK10, KLK12, KLK13, and KLK14 were shown to be differentially expressed at the mRNA or protein levels within the cancerous tissues or serum of such patients." (PMID 16434994, 2006). "Taken together, out data points out that KLK5 re-expression in non-expressing breast cancer cells results in up-regulation of specific miRNAs which can target critical molecules involved in miRNA biogenesis with subsequent global down-regulation of miRNA expression." (PMID 25593998, 2014). "An extended statistical analysis, including logistic regression and ROC analysis, was carried out in order to evaluate the clinical value of the KLK5 expression down-regulation for the prediction of breast cancer and its discrimination from non-cancer breast lesions in tissue biopsies." (PMID 21906360, 2011).
breast carcinoma (continued). "Taking into consideration that KLK5 proteolytic function is responsible for the catalytic cleavage and activation of several others KLKs, the down-regulation of the KLK5 expression in breast cancer tissues possibly signifies the result of a negative regulatory mechanism." (PMID 21906360, 2011). "Interestingly, the results obtained for KLK14 in this study are comparable to those obtained for KLK3, KLK6 and KLK15 in breast cancer and KLK4, KLK5 and KLK10 in ovarian cancer, in that high expression of these kallikrein genes also correlated with patient prognosis." (PMID 12439719, 2002). "High KLK5 expression significantly correlated with worse RFS in breast cancer with lymph node (LN) positivity, suggesting that downregulation of KLK5 may have no clinical significance in breast cancer without accurate subtyping." (PMID 38090381, 2023).